C4A (complement C4A (Chido/Rodgers blood group))
Diseases named in the same sentence as C4A in open-access papers (continued):
Sharing a sentence is not in itself a finding about the gene and the disease.
schizophrenia (continued). "Schizophrenia has been linked to the immune system, in particular the major histocompatibility complex class III (MHC), variations in complement component 4 (C4), and a risk association with increased expression of the C4A isotype." (PMID 38988452, 2024). "We have highlighted a potential role of C4, and this is now supported by recent evidence that cerebrospinal fluid concentrations of C4A are elevated in two separate cohorts of people with schizophrenia, and inversely related to levels of a synaptic marker." (PMID 37041418, 2023). "C4A and C4B, two isotypes of the human gene, are both upregulated in schizophrenia, with C4A expression higher than C4B." (PMID 35204837, 2022). "Accompanying the metabolic disruption identified in patients with schizophrenia was an increase in several complement effector proteins, including C4a/b, C5, C6, C8a, and C9." (PMID 34741130, 2022). "Transcriptional imputation of SCZ GWAS summary statistics confirmed the increased expression of C4A, BTN3A2 from xMHC in several brain regions associated with schizophrenia, including dorsolateral prefrontal cortex (DLPFC)." (PMID 35250027, 2022). "Schizophrenia patients carry more copies of C4A genes and more of the C4AL form, accounting at least in part for the GWAS signal." (PMID 34552056, 2021). "Our findings are consistent with a specific role for C4A protein in schizophrenia and raise the possibility that its activation product, C4-ana, increases BBB permeability." (PMID 34552056, 2021). "INF-γ induction of C4 protein expression would result in more C4A-type protein in individuals with schizophrenia because they carry more copies of the C4A gene." (PMID 34552056, 2021). "Together, these results suggest that the complement system, particularly C4A, may play a key role in the gene-environment interactions of schizophrenia by modulating the gut microbiota and systemic immune activation status." (PMID 41346597, 2025). "A recent proteomic study reported elevated plasma C4A levels in schizophrenia cases, linking with the genetics and implying that measurement of the C4A isotype may provide a more suitable biomarker than measurement of total C4." (PMID 38505993, 2024). "Complex variations were found in the complement component 4A (C4A) gene in schizophrenia patients." (PMID 31439071, 2019). "As a result, varying levels of C4A and C4B expression in the brain are generated, implicating excessive complement activity in the development of schizophrenia that leads to the reduced numbers of synapses in the brains of individuals with schizophrenia." (PMID 31784692, 2019). "Thus, in humans, the complement system serves diverse immune and neural functions and suggest that abnormal C4A function contributes to schizophrenia pathogenesis." (PMID 30026462, 2018). "We use PAQu to investigate differences in isoform abundance levels between people with schizophrenia and control subjects, confirming a long held hypothesis that levels of the C4A isoform of Complement Component 4 are increased in schizophrenia while C4B is not." (PMID 42079223, 2026). "While multiple previous studies have confirmed the association between the C4A gene and an increased risk of schizophrenia, the intrinsic mechanism underlying the negative correlation between C4B and schizophrenia risk remains unclear." (PMID 41346597, 2025). "However, rodents lack specialized C4 genes, and it was first shown in human in vitro models that the unique link between C4A, excessive synaptic pruning, and schizophrenia could be established." (PMID 36434058, 2023). "Further work to test whether C4A is involved in a shared mechanism between major depression and schizophrenia may also be performed using (for example) a joint GWAS—or phenome-wide association study—to identify loci that harbour one or more SNPs with pleiotropic effects on the two disorders." (PMID 31306407, 2019).
schizophrenia (continued). "Biochemically, C4A and C4B differ at the site that determines what molecules they opsonize in tissues; genetically, the relative strengths of association of C4A and C4B (with NMO and schizophrenia) might reflect the encoded proteins’ differential binding to relevant sites in each tissue." (PMID 29769526, 2018). "We also probed the four complement genes located within the MHC region (i.e. C2, C4A, C4B and CFB) via schizophrenia PRS restricted to SNPs within each of them." (PMID 38649377, 2024). "Moreover, we did not identify any strong correlation between schizophrenia polygenic risk score and predicted C4A expression (data not shown), implying that predicted C4A expression is not a proxy for schizophrenia polygenic risk in the UK Biobank sample analyzed." (PMID 33653435, 2021). "While the C4-complement–microglia axis is seen as a major contributor to synaptic deficits and cognitive dysfunction in schizophrenia, there are currently no clinical trials directly targeting C4A modulation." (PMID 41169352, 2025). "Among these, a negative correlation was observed between plasma lipopolysaccharide-binding protein (LBP) levels and C4A gene copy number was observed in patients with schizophrenia, but not in healthy controls." (PMID 41346597, 2025). "The most significant GWAS signal for schizophrenia in a sample predominantly of European origin lies in the major histocompatibility complex (MHC) and has been shown to link to complement expression, in particular to higher C4A brain expression levels." (PMID 37041418, 2023). "The strongest genetic relationship for schizophrenia is with genetic markers located at the major histocompatibility complex (MHC) locus, which contains four genes that are related to the complement system (complement factor B, C2, C4A, and C4B)." (PMID 33670154, 2021). "Alpha-2-antiplasmin, Complement C4-A and Antithrombin-III were increased in first-onset schizophrenia patients (uncorrected P-values 0.041, 0.036 and 0.013, respectively) and also increased in newborn babies who later develop schizophrenia (P-values 0.0058, 0.013 and 0.044, respectively)." (PMID 29249827, 2017).
autoimmune disease (69 papers, 2005 to 2025). A disorder resulting from loss of function or tissue destruction of an organ or multiple organs, arising from humoral or cellular immune responses of the individual to their own tissue constituents. "They activate the complement pathway, crucial for pathogen clearance, and C4A is implicated in autoimmune disease risk due to its regulatory role in autoimmune responses." (PMID 38835753, 2024). "Much attention has been focused on the roles for low copy numbers of total C4 or C4A deficiency in autoimmune disease and the overexpression of C4A in neurologic disorders." (PMID 34764957, 2021). "Accordingly, homozygous deficiency of C4A has been reported to associate with increased frequency of autoimmune diseases, whereas homozygous C4B deficiency has been associated with increased susceptibility of bacterial and enveloped viral infections." (PMID 29928053, 2018). "SNPs in C4 were considered to be responsible for the differences between C4A and C4B isotypes, Rodgers and Chido antigenic determinants and to be associated with several autoimmune diseases." (PMID 29212248, 2017). "In conclusion, the present meta-analysis provides evidence-based pooled data revealing a significant association between low C4 or C4A CNVs and susceptibility to autoimmune diseases, especially for Caucasian individuals with SLE." (PMID 28205620, 2017). "Although several studies have investigated the association between C4, C4A, and C4B gene copy number variations (CNVs) and susceptibility to autoimmune diseases, the results remain inconsistency for those diseases." (PMID 28205620, 2017). "First, heterogeneity among ethnic groups or disease types was discovered when the association between C4, C4A, and C4B CNVs and autoimmune diseases was investigated." (PMID 28205620, 2017). "In our meta-analysis of 8663 cases and 11099 controls in 16 studies from 12 articles, we drew a general conclusion that C4 and C4A CNVs are tightly associated with autoimmune diseases, especially with SLE." (PMID 28205620, 2017). "While a complete deficiency of C4 is rare, an isotype deficiency of either C4A or C4B is much more commonly observed and has been implicated in several autoimmune diseases." (PMID 26913032, 2016). "Deficiency in C4A has previously been associated to several autoimmune diseases and in adults with upper respiratory infections and pulmonary tuberculosis." (PMID 24638111, 2014). "Accordingly, phenotypic C4A deficiencies have been traditionally associated with susceptibility to autoimmune diseases, whereas C4B deficiencies have shown predisposition to infections with encapsulated bacteria, acute myocardial infarction and stroke." (PMID 22737222, 2012). "For example, the HLA class III region contains clusters of genes such as TNF-α, HSP70, C4A/C4B, and NF-κBIL1 that are seminal in cellular function and are also associated with numerous autoimmune diseases." (PMID 22928105, 2012). "Furthermore, the results suggested that low C4A GCNs (<2) are more associated with apparent risk for autoimmune diseases compared with higher GCNs (≥2) (pooled OR = 1.46, 95% CI: 1.10–1.94)." (PMID 28205620, 2017). "C4A deficiencies are often associated with susceptibility to autoimmune diseases." (PMID 25071773, 2014). "Furthermore, our meta-analysis demonstrated that low GCNs of C4 (<4) or C4A (<2) could lead to increased risk of autoimmune diseases among Caucasian populations." (PMID 28205620, 2017). "For example, C4a is a target of the clinical drug “human immunoglobulin G,” which is used to treat immunodeficiency and a wide variety of autoimmune disorders." (PMID 38898508, 2024). "Recent studies have reported that diversities of C4A and C4B proteins and their gene copy number variations (CNVs) in healthy subjects and patients with autoimmune diseases." (PMID 36420131, 2022).
autoimmune disease (continued). "Some limitations of the current meta-analysis of the potential relationship between C4, C4A, and C4B CNVs and autoimmune diseases need to be addressed." (PMID 28205620, 2017). "Additionally, it has been reported that C4A and C4B copy number variations are related to autoimmune disorders." (PMID 32878183, 2020). "Thus, in this study, a comprehensive meta-analysis was conducted to assess the role of C4, C4A, and C4B CNVs in autoimmune diseases in different ethnic groups." (PMID 28205620, 2017).
lupus nephritis (53 papers, 2009 to 2025). Glomerulonephritis in the context of systemic lupus erythematosus. "Urinary C4a levels were highest in FSGS patients compared to samples obtained from patients with chronic kidney disease (CKD), ANCA-associated vasculitis, and lupus nephritis." (PMID 26989679, 2016). "Patients with FSGS had higher levels of plasma Ba and C4a compared to healthy controls and patients with antineutrophil cytoplasm antibody- (ANCA-) associated vasculitis or lupus nephritis or healthy individuals." (PMID 26989679, 2016). "Urine C4a levels were higher in FSGS patients than in ANCA-associated vasculitis, lupus nephritis, and CKD patients." (PMID 26335102, 2015). "We found that the levels of Ba and C4a in plasma from patients with FSGS were significantly higher than levels in patients with lupus nephritis, ANCA vasculitis, and healthy controls." (PMID 26335102, 2015). "We also evaluated plasma and urine Ba, C4a, and sC5b-9 in patients with CKD, lupus nephritis, ANCA vasculitis, and in healthy controls." (PMID 26335102, 2015).
COVID-19 (49 papers, 2020 to 2025). A disease caused by infection with severe acute respiratory syndrome coronavirus 2. "Our results showed that the genes AKT3, GFAP, ADCYAP1R1, VDAC1, and C4A have significant transcriptomic alterations in FTD along with the comorbidity status with COVID-19 and breast cancer." (PMID 37834358, 2023). "In accordance with these findings, MASP-2, as well as MBL, C4a, C4, and C5b-9, accumulate in lung tissue of COVID-19 patients." (PMID 33729332, 2021). "HEP6 and HEP7 cells had similar profiles to those in the HEP2 subset but with high expression of acute phase proteins in HEP7 (e.g., CRP, C3, C4a, SAA1, and FTH1; a COVID-19 specific cluster; below) or apoptosis and cellular senescence pathways in HEP6." (PMID 40087773, 2025). "Overall, we found two novel FTD-COVID-19 comorbid genes, GFAP and RTN4, and five novel FTD-Breast cancer comorbid genes, AKT3, GFAP, ADCYAP1R1, VDAC1, and C4A, in this study." (PMID 37834358, 2023). "Similarly, umbilical cords from COVID-19-affected pregnancies showed higher expressions of CFB and C4A compared to controls (Fig. EV1C)." (PMID 39390219, 2024). "A recent preprint study reported that the paraformaldehyde-fixed lung tissue from patients who died of COVID-19 revealed strong expression of complement components MBL, MASP-2, C4a, C3, and the terminal MAC C5b-9, suggesting LP complement hyper-activation occurred in the lungs of COVID-19 patients." (PMID 33811541, 2021). "Also, in lung tissue from patients with non-resolvable COVID-19 (long COVID), elevated mRNA expression of MASP-2 and associated complement factors (C4a/C4b) suggests sustained lectin and classical pathway activity contributing to progressive fibrosis." (PMID 40869200, 2025).
Autoimmunity (34 papers, 2007 to 2026). The occurrence of an immune reaction against the organism's own cells or tissues. "It will be important going forward to carefully interrogate the mechanisms by which HLA-DRB1*03 and C4A deficiency contribute to autoimmunity and IIM." (PMID 36171069, 2023). "In humans, though, a decrease in copy number resulting in lower protein levels was associated with higher risk of autoimmunity, which is contrary to our findings of an increase in C4a expression associated with lacrimal gland inflammation in WT mice." (PMID 33322152, 2020). "The increased incidence of autoantibodies in the homozygous C4A deficient patients supports the role of C4A deficiency in autoimmunity." (PMID 29928053, 2018). "Despite the association of deficiencies in C4 with autoimmunity, laser capture microdissection coupled with gene expression studies demonstrated an increase in C4A expression in ductal cells isolated from minor salivary glands of individuals with SS compared to healthy controls." (PMID 33322152, 2020). "It is also of interest to note that aPL-positive female (human) patients with homozygous C4A deficiency all experienced RPL, which underlies the importance of C4A protein in achieving tolerance or defense against autoimmunity and fetal rejections." (PMID 31134052, 2019). "Activated C4A and C4B tend to interact or interfere with each other in moderating and propagating the activation of complement pathways, and in the fine-tuning of immunologic functions such as the induction of tolerance or suppression of autoimmunity." (PMID 34764957, 2021). "We summarized current knowledge related to the role of C4, C4A, and C4B CNVs in SLE and other systemic autoimmune diseases and determined whether C4 genes are a genetic master key to autoimmunity." (PMID 28205620, 2017).
leukopenia (31 papers, 2012 to 2025). "Observational and case–control studies have found several general inflammatory biomarkers in PANDAS/PANS, including complement activation (high C4a and low C4), leukopenia, increased C-reactive protein, Neuron-specific Enolase (NSE), and serum amyloid A (SAA)." (PMID 40869088, 2025).
diabetes (22 papers, 2008 to 2025). "In the combined analysis of genes unique to DR and those in common with diabetes mellitus at the threshold of <0.05, we identified C2, C4A, CD8A, HLA-DRB5, and HLA-DQA2, which have been associated with lymphocyte-mediated immunity (FDR 2.96 × 10−2)." (PMID 38791494, 2024). "C4A, or complement C4A (Rodgers blood group), was demonstrated to be downregulated in patients with diabetes who showed severe coronary artery stenosis and can serve as a plasma biomarker for predicting the severity of coronary artery atherosclerosis." (PMID 39649955, 2024).
lymphoma (19 papers, 2010 to 2025). A malignant (clonal) proliferation of B- lymphocytes or T- lymphocytes which involves the lymph nodes, bone marrow and/or extranodal sites. "In patients with homozygotic C4A deficiency, lymphomas were significantly more common than in other groups (12.50%, 4/32 in C4A deficient vs. 0.8%, 1/120 in controls OR = 17.00, 95%CI = 1.83–158.04, p = 0.007)." (PMID 29928053, 2018).
Sjögren’s syndrome (18 papers, 2012 to 2025). "The exclusion of chr6:31474000 due to the lack of rsID may have disproportionately affected the results, as these variants tag a 4.1 kb deletion in the C4A gene associated with Sjögren’s syndrome risk (OR = 2.17)." (PMID 40869949, 2025). "Notably, mutations in the genes encoding C2, C3, C4A, C4B have been linked to SLE, and Sjogren’s syndrome has been reported in patients with genetic deficiencies in C1q, C4, and C2." (PMID 32514272, 2020). "These include OAS1, C4A, and IFIH1 for Type 1 diabetes and ID3 and C4 for Sjögren’s syndrome." (PMID 30002654, 2018).
lung carcinoma (17 papers, 2015 to 2026). "Lower expression of the C4A gene might be involved in the lung cancer development because of abnormal inflammatory response." (PMID 39175755, 2024).
rheumatoid arthritis (17 papers, 2010 to 2025). A chronic, systemic autoimmune disorder characterized by inflammation in the synovial membranes and articular surfaces. "C4a was previously isolated from the inflammatory joint fluid of patients with rheumatoid arthritis and identified as the monocyte/macrophage migration inhibitory factor." (PMID 24789665, 2014).
Sepsis (17 papers, 2011 to 2025). Sepsis is defined as life-threatening organ dysfunction caused by a dysregulated host response to infection. "In general, complements C4 and C3 consumption has been observed in septic patients, which is mirrored in the generation of increased levels of complement activation products, including the anaphylatoxins C4a, C3a, and C5a that are associated with severity and mortality in sepsis." (PMID 34903692, 2022). "In clinical studies of severe sepsis, C3 and C4 were reduced because C3 and C4 are degraded and activated to C3a and C4a, respectively." (PMID 40539044, 2025). "Sepsis can stimulate complement activation in both humans and animals, resulting in increased levels of C3a, C4a, and C5a in plasma." (PMID 23233853, 2012). "Complement activation occurs during sepsis in human, leading to the generation of anaphylatoxins including C3a, C4a, and C5a." (PMID 23233853, 2012). "Moreover, systemic infections like sepsis were found to activate complement, consuming C3 and C4 and generating enhanced levels of C3a and C4a especially in patients succumbing to sepsis." (PMID 26303896, 2015). "C4 activation, manifested as decrease of C4 or increase of C4a, was also reported in other clinical studies of severe late septic shock (42 patients), clinically suspected sepsis on admission (43 of 47 patients), severe sepsis and septic shock (50 patients)." (PMID 23049598, 2012). "As sepsis progresses, complement activation by considerable release of cytokines (TNF-α, IL-6, IL-10, etc.)produced enormous components, such as C3a, C4a, and C5a, and further consumed the pool of complement C3 and C4." (PMID 23091606, 2012).